APOE (apolipoprotein E)
Diseases named in the same sentence as APOE in open-access papers (continued):
Sharing a sentence is not in itself a finding about the gene and the disease.
cancer (continued). "It has been shown that apolipoprotein B (apoB) and apoE rich lipoproteins are taken up by a receptor-mediated pathway in primary podocytes isolated from a human carcinoma kidney, and recently albumin was shown to be endocytosed by human podocytes in vitro and in vivo." (PMID 21949853, 2011). "The APOE genotype may modulate long-term cancer-related toxicity through various pathways." (PMID 41465180, 2025). "However, APOE expression and ApoE levels appear relevant to numerous cancers." (PMID 40149482, 2025). "This clearly underscores how suppressing ApoE may fuel cancer progression." (PMID 40662483, 2025). "Such a role for apolipoprotein E could be pivotal in understanding the degradation pathways that are enhanced or inhibited in the context of tumorigenesis, offering insights into the mechanisms through which apolipoprotein E modulates the proteasome function and influences the progression of cancer." (PMID 39456640, 2024). "APOE genotype may modulate long-term cancer-related toxicity through a number of pathways." (PMID 36441715, 2022). "In addition, liver X receptor β (LXRβ) is overexpressed in PTC and induce the expression of its target genes including APOC1, APOC2 and APOE, which may activate lipid metabolism and protein synthesis, thus facilitating cancer cell proliferation." (PMID 36506554, 2022). "Finally, this retrospective study only investigated the relationship between blood lipids and APOE polymorphisms and cancer and CVD, but did not include other biochemical or molecular markers, such as inflammatory markers or ncRNAs." (PMID 36057714, 2022). "Moreover, ApoE is upregulated and exerts biological functions in various cancers." (PMID 35892323, 2022). "Meanwhile, APOE not only plays the role in lipid transport, storage, utilization and excretion in different organizations, it can also participate in the regulation of various diseases such as schizophrenia, coronary heart diseas, diabetic nephropathies, Alzheimer's disease and malignant tumor." (PMID 35371313, 2022). "Furthermore, pretreating cancer cells with apoE inhibited their growth in mouse models." (PMID 36341364, 2022). "Moreover, APOE-related signalings in cancers can participate in regulation of immunity." (PMID 35371313, 2022). "Furthermore, apoE may also inhibit cancer cell proliferation and angiogenesis due to its high affinity for heparin and proteoglycans." (PMID 32306242, 2020). "We thus assume that ApoE KO iiself may be significant for cancer cell growth." (PMID 31275318, 2019). "However, further study is needed to investigate the role of ApoE in cancer cachexia." (PMID 31788012, 2019). "Thus, it is noteworthy that ApoE knockout and knockdown led to decreased expression of cyclin D1 and its associated proteins CDK4 and CDK6, in urethane-induced lung tumors, lung metastases, and cancer cell lines." (PMID 31275318, 2019). "Therefore, this duality of ApoE activity on cancer cells is tissue-specific." (PMID 29567987, 2018). "However, they did not compare the changes of circulating lipid levels across APOE gene ε2/ε3/ε4 genotypes, which would be of importance to provide background data to infer causality between circulating lipids and cancer risk." (PMID 25820350, 2015). "Importantly, because this analysis was adjusted for APOE ε4, these results also suggest that cancer history-associated later age of AD onset is independent of this risk factor." (PMID 25400589, 2014). "Thus, while cancer history is associated with a measurable delay in AD onset independent of APOE ε4, the underlying mechanism does not appear to be cancer-related preservation of GMD." (PMID 25400589, 2014). "However, ApoE also performs other crucial functions, and aberration of these functions may lead to cancer." (PMID 19455140, 2009).
cancer (continued). "Although care should be taken when extrapolating data from cultured cancer cells to in vivo situation, the effect of psychotropic drugs on lipid biosynthesis along with elevated ApoE expression and cholesterol transport could represent an important psychopharmacological effect of these drugs." (PMID 19715613, 2009). "Apolipoprotein E (ApoE) facilitates lipid transport between the brain and plasma, enabling drug delivery via LDL receptors on cancer cells." (PMID 40771723, 2025). "FTO can inhibit the expression of apolipoprotein E (APOE) and repress the glycolysis and cancer growth in an m6 A-dependent manner." (PMID 40483535, 2025). "For example, APOE, PLAU, CDK1 and MUC1 were significantly higher in TNBC tissues than in cancer-parasite tissues, whereas PDGFRB, RET, ROCK2, CCND1 and PPARA were significantly lower in TNBC tissues than in cancer-parasite tissues." (PMID 38329441, 2024). "The TIMER database was used to analyze the correlation between mRNA expression of APOE, BGN, BST2, and C1QB and infiltrating immune cells in cancer tissues." (PMID 39650066, 2024). "Our results extend these implications to PDAC, highlighting the importance of the spatially correlated crosstalk between CTHRC1+GREM1+ myCAF and SPP1+APOE+ TAM that drive fibrosis, immunosuppression, and EMT in PDAC and potentially other cancers." (PMID 39075108, 2024). "Different from previous reports, APOE was found to be a protective factor for the prognosis of LUAD, while it was reported to promote cancer proliferation and migration and contribute to an aggressive clinical course in patients with LUAD." (PMID 38022584, 2023). "A greater understanding of the direct interactions between APOC1, APOE, RAB42, and TREM2 in cancer is, however, required due to the paucity of studies in this area." (PMID 36908705, 2023). "Consistently, previous studies have shown that SPP1, APOE, C1QA, C1QB, and C1QC are significantly elevated in the plasma of patients with cancer." (PMID 37187751, 2023). "We found expression of genes involved in cancer proliferation (PARP14, VMP1, APOE) in the mBc4 cluster." (PMID 36153593, 2022). "Compared to healthy individuals, patients with BC have an increased level of ApoE in the serum, which is related to the TNM stage for the assistance of cancer progression." (PMID 36506554, 2022). "The same trend was detected for apolipoprotein C-III (APOC3), while apolipoprotein E (APOE) and apolipoprotein A-II (APOA2) were more abundant in cancer coronas for L2 and less abundant for L1 and L3, respectively." (PMID 36142503, 2022). "However, the effect of APOE polymorphisms on cancer risk is not yet established." (PMID 36057714, 2022). "COG112 is an apolipoprotein E (apoE)-mimetic peptide which inhibits SET-Rac1 interaction resulting to decreased cell migration and invasion of cancer cells." (PMID 34230583, 2021). "The addition of benign cell lysate resulted in a significant increase of MMP9, VEGFA, ApoE, ANG, and MMP10, and the addition of cancer cell lysate resulted in a significant increase of MMP9, CA9, PAI1, ApoE, A1AT, ANG, and MMP10." (PMID 34204951, 2021). "The results showed that APOE, CTSD, LGALS2, and TMEM176B expression in normal tissues was significantly higher than that in cancer tissues (P < 0.01)." (PMID 34873574, 2021). "Long-lived Ghr–/– mice have elevated subcutaneous fat mass, APOE and insulin sensitivity of cardiac and skeletal muscle, but lower body weight, plasma cholesterol, IGF-I, plasma insulin, glucose tolerance, and cancer." (PMID 34074802, 2021). "When connecting clinical deficits and genes, we identified five clusters that give insights into the biology of frailty: cancer, glucocorticoid receptor, TNF-α, myostatin, angiotensin converter enzyme, ApoE, interleukine-12 and −18." (PMID 31332237, 2019).
cancer (continued). "The predictive model for post-EBB difficult hemostasis in the present study was developed based on 7 predictors, including histological type of cancer, lesion location, pulmonary infection, neutrophil percentage, APTT, LDL-C, and apolipoprotein-E." (PMID 30931321, 2019). "Smoking, pulmonary infection, histological types of cancer, lesion location, neutrophil percentage, CRP, APTT, HDL-C, alanine aminotransferase, and apolipoprotein-E were statistically different as assessed by univariate analysis." (PMID 30931321, 2019). "These variables were lesions location, cancer histological type, pulmonary infection, neutrophil percentage, APTT, HDL-C, LDL-C, and apolipoprotein-E." (PMID 30931321, 2019). "TFF2 suppresses IMC/MDSC proliferation in part through downregulation of cyclin D1 (and possibly through upregulation of cell-bound ApoE) thus reducing MDSCs and liberating anti-tumorigenic CD8+ T cells to inhibit the development of cancer." (PMID 26841680, 2016). "As a central regulator in cholesterol metabolism, apolipoprotein E (APOE) is increasingly recognized as playing a potent inhibitory role in angiogenesis and cancer cell growth." (PMID 25820350, 2015). "This is partly due to the surprising lack of research focused on ApoE isoforms in various cancers, which would allow some more direct comparisons with what is known with AD." (PMID 40149482, 2025). "Silencing of Jun and LRP1 effectively inhibited the pro-migratory effects of ApoE, further highlighting its role in CRC progression, but as has been seen in other cancer types, in studies of this type, APOE genotype or examination of individual ApoE isoforms was not investigated." (PMID 40149482, 2025). "In MiaPaCa-2 cancer cells, cerivastatin, pitavastatin, and simvastatin increased the expression of the APOC1 gene, the product of which, together with APOE and other apolipoproteins, is an essential component of high-density lipoprotein (HDL), very low-density lipoprotein (VLDL), and chylomicrons." (PMID 40722786, 2025). "We explored them utilizing the pathway activity module of the GSCALite platform to determine whether these six genes (TYROBP, FCER1G, CD48, LST1, APOE, and APOC1) act through specific cancer pathways." (PMID 38515073, 2024). "In our study, we observed co‐localisation of APOE+ TAMs and MMP7+ cancer cells in the TME." (PMID 39187937, 2024). "Despite tissue resident (TR) or monocytic origin of TAM, they may collectively share a core transcriptomic signature comprising: APOE, complement component genes (i.e. C1QA, C1QB, C1QC), and cathepsin (CTSB, CTSD) across several cancer types." (PMID 37342322, 2023). "In addition, SERPINC1, APOA4, APOE and ITIH4 are described deviated in the serum of hyperplasia or cancer patients by two teams." (PMID 37091170, 2023). "Its expression was detected together with APOE, APOC1 (apolipoprotein C1), FABP5 (fatty acid binding protein) and LIPA (Lipase A), genes involved in lipid transport and metabolism and highly detected in breast, sarcoma, colon, lung and other cancers." (PMID 37342322, 2023). "However, one of best highlight of this research is that we used APOE inhibitor-COG 133TFA for cell and mice verification in cancer for the first time." (PMID 36147474, 2022). "Lifestyle factors such as physical activity can mitigate the effect of APOE genotype on measures of clinical interest in individuals without a history of cancer." (PMID 36441715, 2022). "Apolipoprotein E (apoE), a known immune suppressant is strikingly elevated in many human tumors, but its role in cancer immunology is not defined." (PMID 36341364, 2022).
cancer (continued). "The present data indicate that the switch to aerobic glycolysis is independent of age or ApoE genotype, similar to the Warburg effect in cancer, wherein increased aerobic glycolysis is observed despite functional mitochondria." (PMID 35987203, 2022). "APOE, BDNF, and COMT candidate genes have demonstrated influence on neurocognition in oncology populations, though limited data exists specific to pediatric cancer and CNS tumor populations." (PMID 35814456, 2022). "There is a positive correlation between APOE and APOA1 across many of the analyzed cancers." (PMID 37304007, 2022). "In addition, we found that macrophage subpopulations (clusters 1, 5, 7, 8, and 9) from cancer tissues expressed a certain number of immunosuppressive genes, such as VEGFA, MMP14, MMP19, S100A2, APOE, HMOX1, SLAMF7, SIRPα, LAG3 and IL18." (PMID 36158683, 2022). "Moreover, APOE, a representative component of HDL, is also released via EVs from cancer and neuronal cells." (PMID 33808296, 2021). "There is increasing evidence of potential genetic (APOE, COMT, BDNF), plasma (e.g., inflammatory molecules, circulating microRNAs, exosomes, short-chain fatty acids and others), cerebrospinal fluid and neuroimaging biomarkers of CRCI in cancer patients." (PMID 34970595, 2021). "In contrast, the roles of apoE secreted by cancer cells in the melanoma carcinoma model are not the same." (PMID 32306242, 2020). "In our study, plasma concentration of ApoE was downregulated in cancer cachexia patients compared to non-cancer cachexia patients regardless of genders and cancer types, indicating its important role during the progress of cancer cachexia." (PMID 31788012, 2019). "Although APOE ε4 did not affect the overall risk for CRN, there was a trend towards a protective effect in patients with right-sided cancer when compared to those with left-sided carcinoma." (PMID 25029444, 2014). "Another study showed that activation of the LXR/ApoE axis in murine models reduced myeloid-derived suppressor cell (MDSC) populations, promoted cytotoxic T cell responses, and enhanced the efficacy of immunotherapies across multiple cancers, suggesting the immunomodulatory function of APOE." (PMID 40745073, 2026). "Cancer and organismal injuries were the top two diseases and function categories that were predicted to increase, along with neurological (HAND2), hepatic system (APOE, CACNG4, CAMK2B), respiratory system (WNT16), and skeletal muscle developmental disorders (ADD2, HAND2)." (PMID 39508990, 2025). "Some recent studies have reported the expression of these genes (e.g., POSTN, APOE) in subsets of ESCC fibroblasts and macrophages, suggesting the existence of these subsets in ESCC microenvironment, but their role in how they interact with cancer cells or immune cells are largely unexplored." (PMID 36709495, 2023). "We also determined that TREM2+ TAMs highly expressed soluble factors such as SPP1, APOE, C1QA, C1QB, and C1QC, which suggested that this TREM2+ TAMs subset may be exocrine or paracrine for establishing the microflora critical for cancer cell invasion and the metastasis environment." (PMID 37187751, 2023). "Furthermore, to the best of our knowledge, there are no literature reporting any relationship between APOE polymorphisms and the risk of CVD and cancer in the southern China population." (PMID 36057714, 2022). "In addition to ABCG2, APOE and LFER reportedly play a role in cancer stem cells." (PMID 35277124, 2022). "Notably, the APOE transcript was upregulated in 6 cancers, while the expression of ANPEP was downregulated in seven cancers, and it may have oncogenic and antitumor effects." (PMID 35141230, 2021). "Increased APOE expression in hyperplasia and cancer are not fully understood." (PMID 25741405, 2015).
cancer (continued). "CA+ was also associated with later age of AD onset (P < 0.001), independent of apolipoprotein E (APOE) ε4 allele status, and individuals with two prior cancers had later mean age of AD onset than those with one or no prior cancer (P < 0.001), suggesting an additive effect." (PMID 25400589, 2014). "However, no pan-cancer analysis has been conducted specifically for the APOE gene." (PMID 37304007, 2022). "As indicated from the correlation analysis, the expression of APOE showed a negative correlation with PD-1 and TIGIT in carcinomas." (PMID 36147474, 2022). "The results demonstrate that the storage of the urine samples at room temperature for >120 min significantly increased the levels of MMP9, APOE, ANG, and MMP10, which could change the final results (positive or negative to cancer)." (PMID 39857022, 2025).